INS (insulin)
Diseases named in the same sentence as INS in open-access papers (continued):
Sharing a sentence is not in itself a finding about the gene and the disease.
diabetes (continued). "Of the 497 patients, 180 were insulin-treated diabetes mellitus, 94 non-insulin-treated diabetes mellitus, and 223 patients without diabetes mellitus groups (diabetes mellitus 55.1%)." (PMID 33225841, 2021). "Therefore, 3-week CR maintained blood insulin levels and improved glucose tolerance with decreased hepatic IDE levels in an animal model of late-stage diabetes." (PMID 33916828, 2021). "Furthermore, the cells were capable of GSIS as well as containing dense core Insulin granules and the capacity to ameliorate an STZ model of diabetes when transplanted into mice comparable with previous in vivo transdifferentiation attempts." (PMID 33666218, 2021). "HBOT was shown to improve tissue oxygenation and insulin sensitivity in hyperglycaemic overweight and obese men but is not practical for long term management of diabetes because it is expensive, inconvenient to administer and carries risks of barotrauma." (PMID 34260650, 2021). "Taking advantage of the possibility of tracking these dedifferentiated β-cells in lineage-tracing experiments in mouse models of diabetes, Wang and colleagues demonstrated that insulin therapy stimulates in vivo the redifferentiation of the dedifferentiated β-cells into mature NGN3−/INS+ β-cells." (PMID 33921851, 2021). "Future work could address this by investigating regional heterogeneity of the effects of insulin and IGF-1 signaling on brain myelination, as well as relating insulin action to myelination in animal models of obesity or diabetes." (PMID 33669242, 2021). "It is also clear that diabetes technology, whether it is CGM, insulin pump therapy, or closed-loop systems, cannot overcome all of the physiological and pharmacological challenges of pregnancy." (PMID 33512267, 2021). "Diabetes mellitus is a chronic condition that occurs when the pancreas do not create enough insulin, or when the body cannot use the insulin adequately." (PMID 34926852, 2021). "Many of the earlier studies did not distinguish between type 1 and 2 diabetes, and often did not make clear from the methods section the number of patients from each group, or which patients were on insulin treatment (14/18 complied)." (PMID 34621152, 2021). "In the setting of diabetes, a metabolic shift in cardiomyocytes occurred due to insulin resistance or lack of insulin, whereby fatty acid uptake and β-oxidation are increased to maintain ATP production." (PMID 33762571, 2021). "Another possible mechanism for the insulin secretion impairment is a down regulation of the medium and long chain FFAs receptors (GPR40) in the β-cell, as observed in hyperlipidemic animal models before the diabetes development." (PMID 33320449, 2021). "In a clinical cohort, patients with CP who had no diabetes and pancreatic calcification showed higher fasting and mixed-meal glucose levels and lower insulin sensitivity compared to healthy controls." (PMID 34566890, 2021). "The purpose of this study was to investigate the effect of lithium on glucose disposal in a high-fat diet-induced type 2 diabetes mellitus (T2DM) and streptozotocin-induced type 1 diabetes mellitus (T1DM) animal model along with low-volume exercise and low-dose insulin." (PMID 33660027, 2021). "There are two primary mechanisms by which diabetes is felt to accelerate the course of CF pulmonary disease: compromised nutrition due to an insulin insufficient catabolic state, and the negative impact of hyperglycemia on lung inflammation and infection." (PMID 34926166, 2021). "Consistent with prior reports, baseline HbA1c, glucose, HOMA-B, use of insulin, number of non-insulin diabetes medications, and percent weight change at two years were all associated with remission in the combined LABS and Look AHEAD cohorts." (PMID 33627633, 2021). "Diabetes mellitus (DM) is a metabolic and endocrine disease of chronic nature which arises from a lack of insulin secretion, action, or both." (PMID 34956587, 2021).
diabetes (continued). "The majority of Qatari patients with diabetes who take diabetes medications other than insulin have lower odds of depression as opposed to those who do not." (PMID 33803134, 2021). "Furthermore, cells were capable of glucose-stimulated insulin secretion (GSIS), a cardinal feature of β-cell function, and ameliorated hyperglycaemia in a streptozotocin (STZ) model of diabetes in mice." (PMID 33666218, 2021). "The prospective study by Trytko & Bennett had symptomatic hypoglycaemia occur in 11 out of 237 HBOT treatments in patients with diabetes mellitus; only two of these occurring in patients not requiring insulin treatment." (PMID 34684171, 2021). "In addition, we found that women in Q1 are significantly more resistant to insulin, as estimated by HOMA-IR, than women in Q5, which is likely to explain the high prevalence of diabetes in Q1." (PMID 34075145, 2021). "Guidelines on second- and third-line medicines and type of insulin for the control of blood glucose levels in non-pregnant adults with diabetes mellitus [Internet]." (PMID 34987559, 2021). "Patients with older age, lower BMI, non-smoking, no insulin injection, without hypertension or hyperlipidemia, lived in Chengdu (with special diabetes care insurance) had higher control rate of all ABC goals." (PMID 34397707, 2021). "While the minipig is frequently used to test new pharmacological agents for diabetes treatment, only few studies have focused on modelling diabetic comorbidities and no studies have been conducted investigating the effects of insulin-induced hypoglycaemia." (PMID 33727615, 2021). "Endogenous insulin insufficiency is more likely in patients who were not overweight at diagnosis of diabetes or required insulin earlier in their course of diagnosis." (PMID 34434951, 2021). "Unlike insulin secretion, disposition index progressively decreases going from normal glucose tolerance to impaired glucose tolerance to diabetes, which we also observed in our study." (PMID 34206745, 2021). "Patients with APS-3 showed higher age (p = 0.001), age of onset of diabetes (p = 0.006) and TSH (p = 0.004) and lower total insulin as U/day (p < 0.001) and U/Kg (p = 0.001), long-acting insulin as U/day (p = 0.030) and U/kg (p = 0.038) and irisin (p = 0.002) compared to T1DM." (PMID 33099763, 2021). "Exercise-stimulated glucose uptake by muscle occurs independently of insulin signal transduction, making exercise an excellent nonpharmacological method for reducing hyperglycaemia in insulin-resistant conditions, like obesity and type 2 diabetes mellitus." (PMID 34682413, 2021). "It is proposed that insulin-dependent diabetics in a fasting state can develop severe ketoacidosis without pronounced hyperglycemia as a consequence of a carbohydrate deficit." (PMID 34437030, 2021). "A 300 mg/day dose in subjects with diabetes resulted in reduced fasting blood glucose levels, although there was no change in insulin levels or HOMA-IR." (PMID 34970150, 2021). "The three-generation family was affected with diabetes, and the proband had early-onset hyperglycemia (≤25 years of age), was not ketosis-prone, and had acceptable C-peptide insulin levels, which allowed her condition to be differentiated from type 1 diabetes." (PMID 35002955, 2021). "Its overexpression in adipose tissues of aP2-SREBP-1c transgenic mice promotes insulin resistance and diabetes mellitus with an increased blood glucose level (>300 mg/dL) that failed to decrease even with insulin therapy." (PMID 33917607, 2021). "Second, certain confounding factors, such as duration of diabetes, categories of anti-diabetic agents, or insulin use were not considered in the present study." (PMID 34645432, 2021). "Interestingly, activation of the HBP impairs insulin-mediated NOS activity, suggesting a role of O-GlcNAcylation in diabetes mediated NOS impairment." (PMID 34381362, 2021). "Diabetes mellitus is divided into two types: insulin-dependent (type 1) and non-insulin-dependent (type 2)." (PMID 34136578, 2021).
diabetes (continued). "By contrast, when insulin was given later (i.e., after 1.5 months of uncontrolled diabetes), the synaptic protein content was not returned to control levels." (PMID 34944588, 2021). "None of the five drugs in the Diabetes (Non-Insulin) treatment group showed a statistically significant difference in utilization by age bracket." (PMID 33843688, 2021). "For example, lipodystrophy and similar fibroproliferative reactions are commonly seen in patients with diabetes who inject insulin without vigilant site rotation." (PMID 34612609, 2021). "As per the World Health Organization (WHO), more than 420 million adults live with diabetes, and most of them do not have insulin homeostasis." (PMID 34853728, 2021). "Other factors, such education, gender, HbA1c, and diabetes duration did not affect the role of insulin on MCI." (PMID 34577866, 2021). "As far as antidiabetic treatment regimen was concerned 40.6% of patients with diabetes were on insulin, 43.5% on oral antidiabetic drugs and 15.9% were on non-pharmacological treatment." (PMID 32776197, 2021). "MS-275, a nonspecific inhibitor of HDAC1 and HDAC3, potentiated insulin secretion in the islets of rats with type 2 diabetes mellitus." (PMID 34301918, 2021). "Intriguingly, incorporation of insulin enhances cell replication, especially in AMSCs without diabetes." (PMID 33968939, 2021). "Together with the relationship between insulin secretion and lack of efficacy on progression to diabetes, our study suggests that upon removal of ALT therapy prediabetes, benefits on β-cell function are unlikely to be maintained." (PMID 34203471, 2021). "If the patient is receiving only basal insulin, with or without other diabetes medications, blood glucose monitoring should be performed when fasting to evaluate the impact of basal insulin on overnight glycaemic control." (PMID 33098260, 2021). "Therefore, insulin is a key gene related to both NFLD and diabetes, as the current results have demonstrated." (PMID 35154608, 2021). "The Brazilian Diabetes Society supports the utilization of trend arrows for insulin dose adjustments in patients with diabetes on basal-bolus insulin therapy, both with multiple daily insulin doses or insulin pumps without closed-loop features." (PMID 33390180, 2021). "There is a lack of clinical trials evaluating the efficacy of different diabetes treatments and specifically no data on insulin therapy in adults with T2DM and cognitive impairment." (PMID 34577866, 2021). "In diabetes which is a chronic metabolic disease, lack of insulin or problems in insulin utilization occur." (PMID 34174790, 2021). "Conversely, the first-phase glucose-induced insulin secretion is reduced in individuals prior to the development of diabetes, and it is more or less absent in those with full-blown disease." (PMID 35011145, 2021). "Although none of these trials achieved their primary outcomes of diabetes prevention, beneficial treatment effects were observed in exploratory analyses of subgroups within the oral insulin immunotherapy trials." (PMID 33515070, 2021). "In addition insulin enhances MBV in healthy skeletal muscle, and this effect is impaired in INOCA-related conditions such as diabetes and obesity." (PMID 34660730, 2021). "The objective of the present study was to examine the independent association between fasting insulin and the inflammatory marker CRP in individuals without diabetes." (PMID 33691751, 2021). "Although the community hospital pharmacy is the most convenient and timesaving place to obtain treatment for diabetes patient, the availability of insulin products in these hospitals was not satisfactory." (PMID 34383816, 2021). "Insulin and synthetic oral drugs hypoglycemic drugs are the most commonly used treatments for diabetes, despite the fact that they do not fully reverse the disease’s complications and have severe side effects." (PMID 34070179, 2021).
diabetes (continued). "A general lack of knowledge regarding type 2 diabetes was reported, including not having enough information about issues concerning diabetes risks, glycemic control, insulin, and blood glucose values." (PMID 33912400, 2021). "With 10,000 readers, this would equate to no >1.0% of all patients with diabetes treated with insulin." (PMID 33794101, 2021). "After endovascular revascularization, limb salvage was poorer for insulin-treated diabetes mellitus (p = 0.046) and non-insulin-treated diabetes mellitus groups (p = 0.011) compared to surgery, but not for patients without diabetes mellitus (p = 0.15)." (PMID 33225841, 2021). "Presence of an atypical fracture was also significant in the development of a non-union, as was presence of diabetes (insulin or tablet depended)." (PMID 34884334, 2021). "The predictors for higher baseline A1C were non-Chinese ethnicity, younger age groups, longer diabetes duration, patients on insulin treatment, polypharmacy use, patients without hypertension, and patients who were not on antihypertensive agents." (PMID 33762665, 2021). "The authors conclude that the burden of disease – diabetes duration, worse glycemic control, and higher number of complications – rather than insulin use determines health status." (PMID 33776906, 2021). "Diabetes mellitus (DM) may be a cofactor in AD progression due to selective impairment in insulin production, metabolism, or signaling, accompanied by significant upregulation of tau hyperphosphorylation, β-amyloid aggregation, inflammation, mitochondrial dysfunction, and oxidative stress." (PMID 34956794, 2021). "Although these female mice were insulin resistant when compared to wild type controls, they did not develop overt hyperglycemia or diabetes by the age of 6 months." (PMID 33917464, 2021). "In individuals with diabetes, cells are unable to receive the insulin signal because either insulin is not present (type 1 diabetes) or the cell is insensitive to insulin and doesn't respond to its presence (type 2 diabetes)." (PMID 34631141, 2021). "Early morbidity and mortality stratified by insulin use and presence or absence of diabetes mellitus." (PMID 33118731, 2020). "Insulin resistance in the proband was observed through biochemical assessment, with insulin >300 uIU/ml without Type 2 diabetes mellitus, as per OGTT results." (PMID 31868206, 2020). "It should be noted that even under fasting conditions, normal individuals have a basal insulin level, but this is lacking in type 1 diabetes mellitus (DM) and insufficient to overcome insulin resistance in insulin-dependent type II DM." (PMID 32962752, 2020). "In mice with severe diabetes, two INS injections at high dose failed to lower the BG concentration to the normal range, suggesting the existence of a considerable level of INS resistance (solid triangles)." (PMID 32382087, 2020). "In June 2014, the U.S. Food and Drug Administration (FDA) approved a new formulation of the Afrezza inhaled insulin powder to act as prandial insulin requirements for non-smoking adults with diabetes who are free of pulmonary disease." (PMID 32785196, 2020). "It is most commonly precipitated by infections, non-compliance to insulin therapy, or first presentation of diabetes." (PMID 32999787, 2020). "However, metformin has gained wide acceptance and has been recommended as a safe alternative to insulin for the treatment of GDM (Guidelines N. Diabetes in Pregnancy." (PMID 32625081, 2020). "Four weeks after diabetes induction, the diabetic animals were allocated into three treatment groups receiving either no insulin or insulin-releasing implants in a high or low dose." (PMID 32832565, 2020). "Diabetes mellitus is a metabolic disorder characterized by excessive glucose levels and less insulin or absent of insulin hormone in the blood circulation." (PMID 32576159, 2020).
diabetes (continued). "Furthermore, Revathy, Subramani, Sheik Abdullah, and Udaiyar showed that hesperetin exhibited an antihyperglycemic effect by reducing blood glucose and enhancing plasma insulin and glycogen levels in an animal model of STZ-induced diabetes." (PMID 32977511, 2020). "Even if the peptide has turned out not to be important in the treatment of diabetes, every phase of C-peptide research has changed our view on insulin and peptide hormone biology." (PMID 32959070, 2020). "Closed-loop systems have been used to optimise insulin delivery in children with diabetes, but they have not been tested in neonatal intensive care." (PMID 31399480, 2020). "In intense exercise in people without diabetes, although the fluctuation of blood glucose is influenced by the pre-exercise diet, the plasma insulin levels can correct the glucose level and restore muscle glycogen." (PMID 33375059, 2020). "With regard to non-insulin therapy of type-2 diabetes, only one diabetes patient of the hyponatremia cohort was treated with incretin mimetics in addition to insulin, none was treated with sodium-glucose-transporter-2 inhibitors." (PMID 32912147, 2020). "The p.Ala586Thr variant carrier was diagnosed at age 11, C-peptide positive (78 pmol/L), negative GADA, IA2A, ZnT8A, with no known family history of diabetes, and treated with insulin." (PMID 32910913, 2020). "Graded deficiency in insulin gene copy numbers leads to a higher proportion of insulin-reactive T cells escaping thymic negative selection in C57BL/6 mice and these cells cause accelerated diabetes in NOD mice." (PMID 33262765, 2020). "Not everyone in the study was taught to self-manage insulin, as it was different from traditional practice and would require further exploration and development for implementation to the wider diabetes population." (PMID 32406854, 2020). "Finally, USF-1-mediated regulation of WBP2 in response to insulin stimulation raises the possibility of WBP2’s involvement in insulin signaling-related diseases such as insulin resistance and diabetes." (PMID 32393834, 2020). "In order to fully understand these aspects, it is important to note that, in diabetes, α-cells do not respond to secretory or inhibitory stimuli (i.e., insulin or glucose) in a coordinated manner." (PMID 33020399, 2020). "There are some limitations to our study, i.e., the small size of the sample, the potential influence of the diabetogenic drug streptozotocin on the sorafenib PK and the lack of insulin treatment of induced diabetes." (PMID 32016844, 2020). "One was a 14-year-old boy who had diabetes for several years and another, a 12-year-old with recent-onset diabetes: both showed evidence of lymphocytic infiltration with the absence of insulin staining in the 14-year-old boy, typical of T1D." (PMID 32839884, 2020). "Insulin was administered to 1,203 (50.33%) patients with diabetes and to 756 (31.64%) patients without diabetes." (PMID 33118731, 2020). "By not titrating insulin doses to blood glucose levels, many children took risks with their diabetes-related health; many teenagers appeared unconcerned about the potential consequences." (PMID 32169923, 2020). "In contrast, patients with diabetes that received insulin had a similar unadjusted mortality rate as those not receiving insulin (OR=1.08; 95% CI 0.62 - 1.88; P=0.765)." (PMID 33118731, 2020). "The presence of Porphyromonas gingivalis in the periodontal pockets affects the glycemic index in diabetes, and the periodontitis-inducing cytokines TNF-α, IL-6 and IL-1β are also insulin antagonists, triggering irreversible changes in the body's immune response and inflammatory state." (PMID 32634783, 2020). "Out of the 34 metabolites, a total of 12 plasma metabolites were associated with different indices of disturbances in glucose metabolism and insulin sensitivity in individuals without diabetes mellitus." (PMID 32124065, 2020).